CLECL1 (C-type lectin like 1)
Description:
Functions in mediating immune cell-cell interactions. Acts as a T-cell costimulatory molecule, enhancing anti-CD3-induced proliferation. May play a role in the interaction of dendritic cells with T-cells and the cells of the adaptive immune response. Expressed in immature dendritic cells, activates downstream signaling, incuding MAPK signaling pathway leading to an induction of the major histocompatibility complex (MHC) class II expression.
Synonyms: DCAL1; formerly CLECL1P
Gene: Transcribed unitary pseudogene on chromosome 12 (9,722,644 to 9,733,030, reverse strand). Ensembl gene ENSG00000184293.
Subcellular location: Cell membrane
Diseases named in the same sentence as CLECL1 in open-access papers:
CLECL1 is named in the same sentence as 4 diseases in open-access papers, as found by Europe PMC text mining. Sharing a sentence is not in itself a finding about the gene and the disease. The quoted sentences say what the papers report.
autoimmune disease (1 paper, 2013). A disorder resulting from loss of function or tissue destruction of an organ or multiple organs, arising from humoral or cellular immune responses of the individual to their own tissue constituents. "For instance, we have 28 individuals with homozygous LoF in CLECL1, which encodes a novel C-type lectin–like molecule expressed by antigen presenting cells and has been hypothesized to modulate risk of autoimmune diseases." (PMID 24367280, 2013).
multiple sclerosis (1 paper, 2024). A progressive autoimmune disorder affecting the central nervous system resulting in demyelination. "In three instances, the credible set for the eQTL included the known multiple sclerosis susceptibility variants: rs3764021 for the expression of CLECL1 in macrophages; rs1059091 for the expression of IFITM2 in CD8+ T cells; and rs10271373 for the expression of ZC3HAV1 in CD8+ T cells." (PMID 38038362, 2024).
type 1 diabetes (1 paper, 2021). "The reason behind a concurrence between type 1 diabetes and MS in observational studies might be shared genes contributing to susceptibility to both diseases (e.g. CLEC16A and CLECL1), instead of a causal relationship." (PMID 32728946, 2021).
CLECL1 also shares sentences with these, for which no sentence is quoted: tumor (1 paper).